PIK3CA (phosphatidylinositol-4,5-bisphosphate 3-kinase catalytic subunit alpha)
Diseases named in the same sentence as PIK3CA in open-access papers (continued):
Sharing a sentence is not in itself a finding about the gene and the disease.
breast cancer (continued). "The phosphatidylinositol-4,5-bisphosphonate 3-kinase catalytic subunit alpha (PIK3CA) gene, located in the long arm of chromosome 3 (3q26.32), is mutated in approximately 27% of breast carcinomas." (PMID 27129168, 2016). "The phosphoinositide 3 kinase (PI3K)/Akt/mammalian target of rapamycin (mTOR) (PAM) pathway is frequently activated in breast cancer, with PIK3CA being the most commonly mutated gene of significance in estrogen receptor (ER) positive breast cancer." (PMID 26779371, 2015). "A late mutation was found in PIK3C2B which interacts with PIK3CA, one of the most frequent mutations that has been reported in breast cancer." (PMID 25729435, 2015). "The present study indicated that ER positive breast cancer patients with PIK3CA mutation had poorer outcome." (PMID 25816324, 2015). "It had been reported that PIK3CA mutation was associated with better outcome in ER positive breast cancer." (PMID 25816324, 2015). "In fact, a recent study with head/neck cancer implicated APOBEC3B mutagenesis in activation of the kinase PIK3CA, which is also mutated in a large proportion of breast cancers." (PMID 25848704, 2015). "Correlation between PIK3CA mutation and clinicopathologic characteristics of 152 ER-positive sporadic breast cancer patients." (PMID 25816324, 2015). "Phosphatidylinositol-4,5-bisphosphate 3-kinase, catalytic subunit alpha, PIK3CA, is one of the most frequently mutated genes in breast cancer, and the mutation status of PIK3CA has clinical relevance related to response to therapy." (PMID 26587011, 2015). "This study showed that PIK3CA mutations were more frequent in low-risk luminal breast cancer and were associated with significantly improved 5-year distant relapse-free survival in univariate analysis (HR, 0.76; 95% CI, 0.63–0.91; P = 0.003)." (PMID 25857348, 2015). "The frequency and clinical impact of PIK3CA mutations need to be assessed in homogeneous biological subgroups of breast cancers, as the prevalence and biological implications of these mutations appear to vary in the different subgroups." (PMID 26680641, 2015). "Further, EGFR copy number gain, or PTEN loss or PIK3CA mutation have been shown to promote brain metastases from breast cancer." (PMID 25969993, 2015). "PIK3CA gene, which is frequently mutated in breast cancer, except in the TNBC/basal-like subtype, was also found rarely mutated (in 1/12, 8.3% of samples)." (PMID 25961742, 2015). "Certain studies have provided examples to illustrate that mutations can be associated with good prognosis in patients with ER+ breast cancer, e.g., some PIK3CA mutations." (PMID 26036636, 2015). "Actually, the effect of PIK3CA mutation on the prognosis of breast cancer should be assessed according to different cancer molecular subtypes." (PMID 25816324, 2015). "The present study is one of the largest among those examining the role of PIK3CA mutations in breast cancer." (PMID 26452060, 2015). "PIK3CA mutations were most common in breast cancer, and EGFR mutations were most common in lung cancer." (PMID 26015395, 2015). "This analysis showed 88% and 100% of breast cancer cell lines with PIK3CA mutations and a GI50 < 1μM were sensitive to ARQ 092 or ARQ 751, respectively." (PMID 26469692, 2015).
breast cancer (continued). "In early or advanced HER2-positive breast cancer, PIK3CA mutation or PAM pathway activation is associated with poor prognosis." (PMID 25816324, 2015). "Spontaneous mutations in PIK3CA are a much more common event in breast cancers, with more than a quarter of breast cancer patients harboring a mutation in this gene." (PMID 25757876, 2015). "The PIK3CA p.E42K mutation was present in 40.8% of the initial breast carcinoma, and in 25% of the small cell cancer specimen." (PMID 25671134, 2015). "In breast carcinoma, apparently in line with our findings in endometrial carcinoma (precursor) lesions, mutation in PIK3CA is assumed to be an early event and associated to favorable prognosis." (PMID 25415225, 2015). "In the current study, next-generation sequencing (NGS) and Sanger Sequencing (SGS) was used for the mutational analysis of PIK3CA in 186 breast carcinomas." (PMID 26587011, 2015). "In the present study, the mutation rate of PIK3CA in breast carcinoma was 15.6% (39/250), lower than that reported in white and Japanese populations." (PMID 25816324, 2015). "The phosphatidylinositol-4, 5-bisphosphate 3-kinase, catalytic subunit alpha (PIK3CA) gene is frequently mutated in breast cancer (BCa)." (PMID 25176561, 2014). "PIK3CA mutations are thought to arise early in cancer development and to be selected for throughout breast cancer progression, as they can be found in ductal carcinoma in situ as well as invasive primary breast cancers and metastatic samples." (PMID 24520381, 2014). "In a recent meta-analysis showing a favorable clinical outcome in ERα-positive postmenopausal breast cancer patients with PIK3CA kinase domain mutations, a potential favorable response to endocrine treatment was suggested as one of the explanations." (PMID 24467828, 2014). "In a study which examined the genetic structure of the PIK3CA gene in 452 breast cancer patients, PIK3CA mutations were observed in 33.4% of the breast cancer patients." (PMID 25051360, 2014). "Hotspot mutations in PIK3CA were identified in CTCs from patients with either colorectal or breast cancer in two different studies." (PMID 25222379, 2014). "Our observations indicate that PIK3CA hotspot mutations have limited potential to predict intrinsic tamoxifen resistance in the adjuvant treatment of ERα-positive, postmenopausal breast cancer patients." (PMID 24467828, 2014). "For a collection of over 500 breast cancer samples we found 29.1% PIK3CA mutations, which is consistent with the COSMIC database." (PMID 24658394, 2014). "For example, comparison of pre- and post-trastuzumab treatment of tissue samples in metastatic HER2-amplified breast cancer from patients progressing on trastuzumab allowed determination of mutations in PIK3CA and PTEN arising during treatment." (PMID 24551596, 2014). "A link between the PI3K/mTOR pathway and AR signaling was previously established in prostate cancer and PIK3CA mutations are enriched in ER + breast cancer." (PMID 25103565, 2014). "PIK3CA mutations were more frequently detected in ERalpha+ and PR+ breast cancers (41.1%), than in TNBCs (ER-,PR-, HER2-) (12.5%)." (PMID 25051360, 2014). "An association between AR expression and PIK3CA mutations was observed in a study which examined AR and ER expression and PIK3CA mutational status in 347 breast cancer patients." (PMID 25051360, 2014). "In a study with 547 human breast cancer patient samples and 41 established cell lines, the mutational status of PIK3CA, AKT and PTEN were analyzed as well as the effects of pathway mutations on the sensitivity to PI3K inhibitor LY294002." (PMID 25051360, 2014).
breast cancer (continued). "Phenotypic differences between knock-in and transgenicmodels are also evident, and clinical observations will eventually validate whichmodel more closely represents human PIK3CA mutated breast cancer." (PMID 25192370, 2014). "Here in a patient with progressive metastatic breast cancer, we compared the PIK3CA mutation status of sequentially sampled CTCs to that of tumor cells from two biopsied metastases and DTCs from bone marrow." (PMID 24947048, 2014). "Numerous studies have shown that PIK3CA is the most frequently mutated oncogene in ER+ breast cancer, occurring with a frequency of up to 45% in various tumor series." (PMID 24520381, 2014). "Copy number gain of the PIK3CA appears to be less common than mutation, having been indentified in 1–14% of breast cancers." (PMID 25542038, 2014). "PIK3CA hotspot mutations are found in approximately 25% of breast cancers and can overlap with HER2 amplification." (PMID 24451154, 2014). "In breast cancers driven by HER2 the frequency of PIK3CA mutations or PTEN loss has been described as up to 40%." (PMID 25056500, 2014). "The PIK3CA gene was determined to be mutated in 21.3% of HER2+ breast cancer patients that had been treated with herceptin for one year." (PMID 25051360, 2014). "Some investigators reported better prognosis in certain cancers such as breast cancer with PIK3CA mutations, whereas others suggested that PIK3CA mutations indicated a worse prognosis in colorectal cancer, endometrial cancer and NSCLC." (PMID 24533074, 2014). "Mutations of Akt are relatively rare in breast cancer, however, aberrant activation of either upstream PIK3CA or polymorphism of the PH domain and leucine rich repeat protein phosphatase 2 (PHLPP2) gene can result in Akt expression." (PMID 25051360, 2014). "A potential bias of these cohort studies is that the prognostic value of PIK3CA mutations is analyzed in breast cancer patients who all received adjuvant endocrine therapy." (PMID 24467828, 2014). "PIK3CA mutations are positive prognostic factors in breast cancer, supporting the clinical utility of MPS for the detection of clinically actionable mutations." (PMID 24885028, 2014). "In a study that evaluated the association of PIK3CA status with clinicopathological factors in primary breast cancer, the effect of PIK3CA mutations was analyzed within molecular subtypes." (PMID 25056500, 2014). "We used immunohistochemical analysis to determine PDK1 expression in 241 tumors from patients with breast cancer in which we had previously analyzed PIK3CA mutation status." (PMID 24739482, 2014). "Clinical study of oncogenic mutations in the PI3K/PTEN/AKT pathway reported both the data on mutually exclusive of PTEN loss and PIK3CA mutation in human breast and gastric carcinomas and frequently concordant in breast cancer." (PMID 24551596, 2014). "In a screening of samples from 55 breast cancer patients, PIK3CA mutations or low expression of PTEN was associated with resistance to Herceptin." (PMID 25051360, 2014). "It is unclear how toextrapolate these data when, in breast cancer, PIK3CA mutations are stronglyassociated with an ER-positive phenotype and RAS mutations are extremely rare." (PMID 25192370, 2014). "For single CTC/DTC/tumor mutation analysis, we have chosen to interrogate exons 9 and 20 of the PIK3CA gene, one of the most frequently mutated genes in breast cancer." (PMID 24947048, 2014). "Whereas in a study of 240 patients with early-stage HER2-positive breast cancer treated with adjuvant trastuzumab-based therapy, PIK3CA mutation-positive breast cancer was associated with significantly poorer OS." (PMID 25056500, 2014).
breast cancer (continued). "Double mutants, or cases with two different PIK3CA mutations,have also been observed in breast cancer, albeit infrequently." (PMID 25192370, 2014). "Droplet digital PCR (ddPCR) was used to assess the presence of PIK3CA mutations (in exon 9 and 20) in the blood of estrogen-receptor- and progesterone-receptor-positive early-stage breast cancer patients." (PMID 25222559, 2014). "The clinical relevance of PI3K pathway deregulation should be evaluated in the context of breast cancer molecular subtypes as these subtypes differ in survival outcome, treatment response, and frequency of PIK3CA mutations and PTEN loss." (PMID 25056500, 2014). "Whole exome sequencing of 93 basal-like breast cancers by the Cancer Genome Atlas Network identified PIK3CA mutations in 9 (10%)." (PMID 24708766, 2014). "The concurrent mutation and amplification of PIK3CA frequently occur in all of breast cancer with 42% (18 of 43) of tumors with amplified PIK3CA also harboring a PIK3CA mutation." (PMID 25103565, 2014). "The mutational status of the PIK3CA gene was examined in eighty HER2+ breast cancer patients as well as clinical outcome of the patients after Herceptin treatment." (PMID 25051360, 2014). "Activating mutations and amplification of the PIK3CA gene are commonly found in breast cancer, particularly in ER-positive or HER2-positive disease." (PMID 25542038, 2014). "PIK3CA mutations in the two breast cancer cases (Ca309 and Ca285) were confirmed to be real mutations as the identical mutation of similar frequency was identified in each of these cases after UDG treatment." (PMID 24885028, 2014). "Recently, Beaver and colleagues studied tumor cfDNA to detect PIK3CA mutations and to monitor residual disease after surgery in patients with early stage breast cancer." (PMID 25222559, 2014). "Out of the top ten mutated genes in the large breast cancer investigation of The Cancer Genome Atlas (TCGA), we found mutations in seven of these (PIK3CA, GATA3, MAP3K1, MLL3, CDH1, PTEN, TBX3)." (PMID 24998755, 2014). "PIK3CA (phosphatidylinositol-4,5-bisphosphate 3-kinase, catalytic subunit α) somatic mutations are the most common genetic alteration in breast cancer (BC)." (PMID 24981670, 2014). "In this study, we confirmed the detection of two low frequency actionable mutations in the PIK3CA gene, in breast carcinoma cases." (PMID 24885028, 2014). "Mutations in the gene encoding the p110a (PIK3CA) subunit of PI3K are commonly found in breast cancer." (PMID 23663520, 2013). "We chose MCF-7 breast cancer cells because they harbor a somatic mutation in the PIK3CA gene that confers a constitutively active AKT-mTOR pathway." (PMID 23638184, 2013). "The present study extends our previously published data describing the positive effect of PIK3CA exon 9 and 20 mutations on breast cancer patient survival." (PMID 24229379, 2013). "For instance, approximately 30% of breast cancers are associated with activating missense mutations of PIK3CA, the gene encoding the catalytic p110α subunit of class IA PI3K, which provides cells with a growth advantage and promotes tumor progression." (PMID 24261963, 2013). "We and other teams have found PIK3CA mutations in 10 to 40% of breast cancer cases and AKT1 mutations in less than 10% of cases." (PMID 24229379, 2013). "This study is the first to characterise biomarkers and mutations in the PIK3CA/mTOR pathway in familial male breast cancer noting several novel observations." (PMID 23971979, 2013). "PIK3CA mutations are among the most common mutations, as they are observed in 10 to 40% of breast cancer cases, depending on the breast cancer subtype." (PMID 24229379, 2013). "PIK3R1 has also been recently found to be mutated in breast cancer, but with a considerably lower frequency (about 3%) than PIK3CA." (PMID 24229379, 2013).
breast cancer (continued). "This study extends the previously obtained data concerning the positive prognostic role of exon 9 and 20 PIK3CA mutations in breast cancer." (PMID 24229379, 2013). "Results of PIK3CA mutation status from circulating DNA in this study (two of 27 HER2+ breast cancer patients who received treatment) are at the lower limit of these estimations." (PMID 24252402, 2013). "There is growing evidence in the literature concerning the favorable outcome of PIK3CA-mutated breast cancer, as supported by the results of this study." (PMID 24229379, 2013). "PIK3CA mutations tend to cluster in exons 9 and 20 with exon 20 kinase domain mutations more common in breast cancer and exon 9 helical domain mutations more common in colorectal cancer." (PMID 24066160, 2013). "While most breast cancer studies examined the role of the PIK3CA mutations, less attention has been given to PIK3CA expression." (PMID 24083111, 2013). "PIK3CA mutations were identified in 151 (33.0%) of the 458 samples, in line with previous studies in which PIK3CA mutations were found in 10 to 40% of breast cancer cases." (PMID 24229379, 2013). "PIK3CA mutations were detected in 13 (28%) of 46 plasma-derived and 10 (21%) of 46 serum-derived cfDNA samples from metastatic breast cancer patients." (PMID 23320751, 2013). "Approximately one-third of HER2-positive breast cancers contain a PIK3CA somatic mutation, and PTEN loss is present in up to half of triple-negative breast cancers." (PMID 23662165, 2013). "For the BRAF inhibitor AZ628, PIK3CA mutation predicted resistance when it occurred in the context of a breast cancer or colon cancer cell line (training set)." (PMID 23577104, 2013). "Preclinical data suggested that the compound prevents phosphorylation of AKT and inhibits growth and PI3K signaling in breast cancer cell lines harboring PIK3CA mutations." (PMID 24261963, 2013). "Twenty-six percent of breast cancers and 12% of large intestinal cancers have somatic mutations to PIK3CA, making mutant PIK3CA a popular target for the development of chemotherapeutic agents." (PMID 22912864, 2012). "Activating mutations of the p110alpha subunit of Pi3k, encoded by the PIK3CA gene, have been identified in a broad spectrum of tumours, e.g. breast cancer and glioblastomas." (PMID 23139750, 2012). "For example, AKT signaling is diminished in human breast cancer cell lines and clinical samples harboring PIK3CA mutation." (PMID 22666248, 2012). "PIK3CA-mutated status was associated with markers of good prognosis and with significant improvement in overall (P = 0.03) and breast cancer-specific (P = 0.004) survival." (PMID 22330809, 2012). "We investigated the prognostic significance of PIK3CA mutation status in a series of 452 patients with unilateral invasive primary breast cancer and known long-term outcome (median follow-up 10 years)." (PMID 22330809, 2012). "Several studies of breast cancer suggest that PIK3CA mutations are more frequent in estrogen receptor-alpha- positive (ERα+) breast tumors (30% to 40%) than in receptor-alpha-negative (ERα-) breast tumors (10% to 20%)." (PMID 22330809, 2012). "BEZ235 decreased cell proliferation of breast cancer cell lines with PIK3CA mutations and cisplatin-resistant human ovarian cancer cells." (PMID 22619567, 2012). "The phosphatidylinositol 3 kinase (PIK3) signaling pathway is an important regulator of cell growth, proliferation, cell motility, angiogenesis, and survival, and it has been shown that PIK3CA is the most frequently mutated gene in breast cancer." (PMID 23056620, 2012). "Mutations in the PIK3CA gene are found in up to 40% of human breast cancers and in vitro expression of these mutations in cell lines has suggested that they are oncogenic." (PMID 22666336, 2012). "In breast cancer, activating point mutations in PI 3-kinase have only been found in the PIK3CA gene, although amplification of the PIK3CB gene has also been reported in some cases." (PMID 22970388, 2012).